LINC01943 (long independently transcribed non-coding RNA 1943)
Gene: Long non-coding RNA gene on chromosome 2 (87,439,522 to 87,459,111, reverse strand). Ensembl gene ENSG00000280721.
Diseases named in the same sentence as LINC01943 in open-access papers:
LINC01943 is named in the same sentence as 2 diseases in open-access papers, as found by Europe PMC text mining. Sharing a sentence is not in itself a finding about the gene and the disease. The quoted sentences say what the papers report.
triple-negative breast carcinoma (1 paper, 2022). An invasive breast carcinoma which is negative for expression of estrogen receptor (ER), progesterone receptor (PR), and human epidermal growth factor receptor 2 (HER2). "LINC01943 was upregulated in triple negative breast cancer (TNBC) tissues, which could regulate TGF-β expression to promote tumorigenesis, leading to worse OS." (PMID 36226251, 2022).
cancer (1 paper, 2024). A tumor composed of atypical neoplastic, often pleomorphic cells that invade other tissues. "We found that USP30-AS1 and LINC01943 were two key ICP-related lncRNAs that participate in multiple survival-related ICP-LncCRCTs with different ICPs and immune genes in diverse cancers." (PMID 38485995, 2024).